MTOR (mechanistic target of rapamycin kinase)
Diseases named in the same sentence as MTOR in open-access papers (continued):
Sharing a sentence is not in itself a finding about the gene and the disease.
cancer (continued). "miR-141 and miR-200a targetome were commonly enriched in pathways in cancer, JAK/STAT signaling pathways and interestingly in mTOR and TGF-β pathways." (PMID 25938517, 2015). "The activation of the mTOR and ERK1/2 MAPK signalling cascades plays a fundamental role in cancer progression." (PMID 25952930, 2015). "Among the Kyoto Encyclopedia of Genes and Genomes (KEGG) gene sets, several pathways related to cancer were ranked in the top 10, in addition to “JAK/STAT signaling pathway” and “mTOR signaling pathway, ” which is located downstream of the JAK/STAT cascade." (PMID 25980440, 2015). "Knockdown of mTOR with siRNA reduced the HD1B cell ability to immunosuppress T cells and stimulate cancer cell proliferation." (PMID 25807535, 2015). "Enhanced rRNA synthesis is a downstream effect of many of the signaling pathways that are aberrantly activated in cancer, such as the PI3K/mTOR and MAP kinase pathways." (PMID 26472108, 2015). "HIF-1α also regulates many cancer signaling pathways, including PI3K/AKT/mTOR, Notch, and Myc, to mediate tumor proliferation, invasion and migration." (PMID 25993275, 2015). "However, in the case of EGFR-mutant H1975 NSCLC cells (L858R and T790M positive), our study suggests that alternative EGFR signaling may be occurring mainly through the MAP Kinase and/or PI3K/Akt-stimulated mTOR pathway, resulting in cancer cell proliferation and survival." (PMID 26301867, 2015). "We previously found that expression levels of certain components of mTOR complexes, such as mTOR itself and RICTOR, are upregulated in various human cancers as a result of silencing of specific microRNAs." (PMID 25906254, 2015). "Several signaling pathways, including the MAPK/ERK, PI3K/AKT/mTOR, STAT3, VEGFR and PDGFR pathway, are demonstrated to promote cancer progression." (PMID 26556861, 2015). "Recently, mTOR, a key downstream effector of the phosphoinositide 3- kinase (PI3K)/AKT signaling pathway, has been recognized to play a crucial role in controlling cancer cell growth." (PMID 26375441, 2015). "The genes were significantly enriched in pathways important for cancer development and progression such as Jak-STAT, MAPK, TGF-beta, mTOR signaling pathways, cell cycle and apoptosis." (PMID 25978727, 2015). "The phosphatidylinositol 3-kinase/protein kinase-B/mammalian target of rapamycin (PI3K/AKT/mTOR) signaling pathway has been studied extensively and is activated in a myriad of cancers." (PMID 26347853, 2015). "Interestingly, both AML and renal volume increased during the third year even while on the treatment with adequate Rapamycin plasma levels, which may be due to an adaptive escape mechanism from mTOR inhibition, although this is an uncommon event in non-cancer cells." (PMID 26077033, 2015). "In cancer cells, translation is driven by HSF1 through regulation of ribosome biogenesis, and HSF1-dependent transactivation is regulated by mTOR activity." (PMID 26473447, 2015). "Dysregulation in PI3K/AKT/mTOR, AMPK, and MAPKs pathways are often existent in cancer primarily due to deletion and post-translational modifications." (PMID 26098947, 2015). "Deep explorations revealed that mTOR can interact with a broad spectrum of other biological molecules, such as AKT and PI3K, promoting the cancer cells growth." (PMID 26357655, 2015). "Mcl-1 is finely regulated and targeting canonical signaling pathways with kinases inhibitors such as PI3K/AKT/mTOR and RAF/MEK/ERK inhibitors gave promising results and strongly sensitized cancer cells to ABT-737." (PMID 25627260, 2015). "The PI3K/AKT/mTOR pathway and its crosstalk with the RAS/RAF/MEK/MAPK pathway play a crucial role in cancer cell growth, survival, differentiation, and proliferation." (PMID 25902832, 2015). "Taken together, these data demonstrated that FBXW7 regulates cancer cell EMT, motility and stem-like characteristics possibly via mTOR signaling in CCA cells." (PMID 25749036, 2015).
cancer (continued). "mTOR was reported to inhibit CRC tumor formation and the mTOR pathway also plays a crucial role in cancer biology, including the upstream activator Akt and down-stream molecules S6, 4EBP1 and their phosphorylation proteins." (PMID 26259252, 2015). "One study suggests the selectivity of metformin against cancer cells is due to the activation of AMPK and subsequent inhibition of mTOR signaling to downstream effectors such as S6K1 and 4EBP1." (PMID 25988385, 2015). "It has exhibited anti-proliferative, pro-apoptotic and anti-tumorigenic activities against various cancers by inhibiting Wnt/β-catenin, PI3K/AKT/mTOR, and NFκB signaling pathways." (PMID 26299806, 2015). "Significant correlation between mTOR-dependent upregulation of PCK1 and cell death in different cancer cell lines further emphasizes the physiological relevance of this pathway." (PMID 27551450, 2015). "The importance of colon-specific crosstalk between mTOR and Wnt signalling is underscored by the finding that a wide variety of key components of mTOR signalling are overexpressed in CRC, and differ by cancer stage." (PMID 25388238, 2015). "mTOR and EGFR inhibitors have already been identified as a synergistic combination in various cancer cell types, despite clinically observed toxicity." (PMID 25824484, 2015). "It is well known that cytotoxic agents can induce apoptosis in cancer cells by modulation of MAPK and Akt/mTOR signaling cascades." (PMID 25648333, 2015). "We showed that mTOR and phosphodiesterase 4D (PDE4D) strongly correlate in resistant EGFR-mutant cancer cell lines." (PMID 26639561, 2015). "This mutual DGKζ and mTOR regulation resembles that of mTOR and PI3K; whereas in normal cells, such axes help to maintain homeostasis, in cancer cells they mediate the cell rewiring that contributes to drug resistance." (PMID 26302180, 2015). "PTEN is a well-known tumor suppressor in numerous cancers and normal tissues and regulates the AKT and mTOR signaling pathways." (PMID 25738494, 2015). "In cancer cells, metformin stimulates AMPK, with the inhibition of the mammalian target of rapamycin (mTOR)/ribosomal S6 kinase pathway and inhibition of pathological cell cycle progression, cell growth and angiogenesis." (PMID 29147424, 2015). "We found that rapamycin significantly inhibited MMP-2, but not MMP-9, compared with the control, suggesting that mTOR signaling plays significant roles both in maintaining NPC CSCs and in cancer progression." (PMID 26202311, 2015). "The relationship between metabolic rates and cancer incidence appears to be supported by evidence that suggests metabolism drives tumorigenesis, which could be curbed by decreased metabolic demands through treatment of animals with mTOR inhibitors or by inhibition of mitochondrial respiration." (PMID 26056367, 2015). "The mTOR inhibitors everolimus and temsirolimus have been approved by the U.S. Food and Drug Administration (FDA) for other cancer types and are under clinical investigation in solid tumors." (PMID 26510912, 2015). "Cancer-related genes with significant up-regulation in all ATCs included MYC, mTOR, PRKCA and TGFB1." (PMID 26680454, 2015). "It promotes cell migration which is necessary for cancer cell proliferation, migration and invasion through activation of the PI3K/AKT/mTOR and Raf/MEK/ERK pathways." (PMID 26497366, 2015). "Pathway enrichment analysis was performed with the common 116 genes and most were found to be enriched in pathways related to cancer, TGF-beta signaling, the cell cycle, apoptosis, MAPK, mTOR and VEGF signaling." (PMID 25978727, 2015). "In order to further study the mechanism of glycolysis in NSCLC regulated by mTOR, we examined pyruvate kinase isoenzyme type M2 (PKM2), a key player in promoting cancer metabolism by using Western blotting." (PMID 26176608, 2015).
cancer (continued). "HER family pathway activation (p-erbB2, p-EGFR, p-HER3) was common in the primary and MBC samples, with downstream activation of p-mTOR and p-STAT3 seen in several patients’ cancers." (PMID 25871911, 2015). "Although the Myc oncogene is known to directly regulate the protein synthesis machinery, recent reports suggest that, in Myc-driven cancers such as AML, Myc enhances protein synthesis by activating mTOR-dependent phosphorylation of 4EBP1." (PMID 26473447, 2015). "PTEN is commonly inactivated in human cancers and acts as a key regulator of the PIP3/AKT/mTOR pathway." (PMID 25738494, 2015). "FGFR3 is one of the receptors that promote cell survival by stimulating PI3K/AKT/mTOR signaling, and has been shown to activate AKT and ERK in human cancers." (PMID 26078354, 2015). "Cancer cell properties like increased proliferative capacity and anchorage-independent growth are mediated in part through PI3K/AKT/mTOR signaling, which controls cell growth through protein synthesis." (PMID 25749517, 2015). "When Gli1 was activated by mTOR signalling through the SMO-dependent canonical pathway, S6K1-mediated Gli1 phosphorylation prevents Gli1 from SuFu-mediated inhibition in the cancer cells." (PMID 26218750, 2015). "The rationale of this strategy is based on the fact that mTOR inhibition will block the downstream oncogenic targets of mTOR signaling proteins including S6K and 4E-BP1 which are critically involved in cancer cell protein synthesis and proliferation." (PMID 25792980, 2015). "In the context of cancer pathogenesis, GOLPH3 was shown to enhance signaling through the mammalian target of rapamycin (mTOR)." (PMID 25691054, 2015). "For NRAS mutant cancers the combination of MEK and the dual PI3K/mTOR were described to be synergistic." (PMID 26544513, 2015). "Everolimus inhibits the ability of mTOR to phosphorylate S6K1 and 4EBP1, thereby inducing G0/G1 arrest and inhibition of cell-cycle propagation in cancer cells." (PMID 25886409, 2015). "The link between growth factor dependent activation of PI3K/Akt/mTOR signalling and downstream up-regulation of MMP gene expression has been shown in vitro for several cancer types." (PMID 26652716, 2015). "This makes metformin an attractive candidate for the treatment of NRAS mutant cancer, where the constitutively active NRAS signals through the PI3K/AKT/mTOR pathway." (PMID 25504439, 2015). "Therefore, metformin plus mTOR inhibitor might be a rational strategy to treat cancer." (PMID 24457597, 2014). "Phospho-mTOR, pp70S6K, pPDK1, PI3K, pPTEN, and PTEN levels were further reduced in cancer cells cotreated with Sal and MK-2206, when compared to cancer cells treated with either MK-2206 or Sal alone." (PMID 25114899, 2014). "Phosphorylation of DEPTOR by CK1α leads to βTrCP-mediated proteasomal degradation of DEPTOR resulting in activation of mTOR signaling, which is consistent with DEPTOR down-regulation and mTOR activation found in many cancers." (PMID 24904820, 2014). "Metformin radiosensitised FSaII mouse fibrosarcoma cells and human breast cancer MCF7, lung cancer cells A549 and H1299 and preferentially killed cancer stem cells, by activating AMPK and suppressing mTOR." (PMID 25427448, 2014). "mTOR activation mediated by MHY1485 was able to restore the expression of c-Myc, hnRNPA1, and hnRNPA2 in OA-treated cancer cells." (PMID 24626155, 2014). "Nowadays, the paradigm of chemotherapies in cancer patients has changed with the development of chemotherapy such as capecitabine and targeted agents including tyrosine kinase inhibitors (TKI) and mammalian target of rapamycin (mTOR) inhibitors." (PMID 25061471, 2014). "In many cancers, the receptor tyrosine kinase/PI3K/AKT/mTOR pathway, an important intracellular pathway, is overactive." (PMID 24972138, 2014).
cancer (continued). "The interplay between both mTOR complexes and the PI3K/Akt signalling pathway is support for the consistent upregulation of the mTOR network in numerous cancers." (PMID 25202348, 2014). "The PI3K/Akt/mTOR pathway is overactivated and heat shock protein (HSP) 90 is overexpressed in common cancers." (PMID 24796583, 2014). "In cancer patients, dual inhibition of BRAF/MEK/ERK1/2 and PI3K/AKT/mTOR pathways is in phase I clinical trials." (PMID 24970815, 2014). "Survivin, an apoptosis-inhibitory protein that is over-expressed in multiple cancer types and plays critical roles in regulating apoptosis, cell proliferation and survival, was found to be a direct downstream target of the PI3K/Akt/mTOR pathway." (PMID 24387108, 2014). "Given the evidence for an mTOR–eIF4A–IRES pathway, we tested how hippuristanol and PP242 influenced cancer cell cycle, cell death and cell proliferation." (PMID 25392452, 2014). "Since AKT/mTOR appears to play a central role in signaling caused by many growth factors to regulate cell proliferation and survival, some mTOR inhibitors, such as rapamycin and CCI-779, are tested as anti-cancer agents." (PMID 24970807, 2014). "A variety of cancer cell lines, including ER+ MCF7 and triple negative MDA-MB-486 expresses elevated mTOR signaling and Notch activity." (PMID 25566499, 2014). "In the current study, using CaP-RR model and cancer cell biology techniques, we present novel insight into the effects of a combination treatment with PI3K/mTOR inhibitors and RT as well as the putative mechanisms." (PMID 25275598, 2014). "In case of cancer cells that compromise therapeutic success, targeting inhibition of PTEN-related PI3K/AKT/mTOR pathway has been shown to prevent tumorigenesis and progression." (PMID 25426449, 2014). "Variations in intracellular calcium, critical events that regulate cancer cell proliferation and progression, may be explained by the complex effects of calcium on different cancer cell signaling pathways, including the Ca-calmodulin protein kinase cascade, Akt, mTOR and TGFβ1." (PMID 24670043, 2014). "Recent findings suggested that eIF4E is a key determinant of PI3K/Akt/mTOR- and Ras/Raf/MAPK-mediated tumorigenic activity, and that targeting eIF4E should have a major impact on these pathways in human cancers." (PMID 25277198, 2014). "Arguably, targeting activating mutations in the phosphoinoside-3-kinase (PI3K)/AKT pathway have proven to be a viable strategy for inhibiting mTOR, however, in cancers that are mutant for LKB1, AMPK-mediated regulation of mTOR will be compromised." (PMID 25436981, 2014). "Numerous agents targeting mTOR, PI3K, growth factor receptors, and related tyrosine kinases, RAS, RAF, and B-RAF, S6K, MEK1/2 have been tested to treat cancer." (PMID 25361007, 2014). "Network analysis shows that the genes harboring disruptive SNVs were involved in molecular mechanisms of cancer, and the signaling pathways of LPS-stimulated MAPK, IL-6, iNOS, EIF2 and mTOR." (PMID 24416147, 2014). "Accordingly, inhibition of mTORC2 (e.g., with mTOR kinase inhibitors) will down-regulate FLIPS levels and sensitize cancer cells to undergo death receptor-induced apoptosis." (PMID 25594024, 2014). "The mTOR pathway has been reported to be central to cancer progression and rapamycin (RPM) has been shown to suppress carcinogenesis by decreasing mTOR activity." (PMID 24944633, 2014). "In cancer cell lines, AMPK activators, such as metformin, can significantly inhibit cell growth by induction of cell cycle arrest through AMPK activation, and this effect may be associated with suppression of anabolism through inhibition of mTOR by phosphorylating tuberous sclerosis 2 (TSC2)." (PMID 25244018, 2014). "The mammalian target of rapamycin (mTOR) is a key downstream regulator of the phosphatidylinositide 3-kinase (PI3K) pathway, one of the most commonly activated signaling pathways in cancer." (PMID 24708766, 2014).
cancer (continued). "As PI3 K and mTOR activities are commonly upregulated in various cancers, PI3 K inhibitors and rapamycin analogues are investigated as inhibitors of cancer progression in preclinical and clinical trials." (PMID 24891760, 2014). "Inhibition of Mnk-mediated eIF4E activity is believed to have a major impact on the PI3K/Akt/mTOR and Ras/Raf/MAPK pathways in human cancers." (PMID 25277198, 2014). "Inhibiting mTOR signaling down-regulates PKM2 expression and suppresses cancer metabolism, as demonstrated by decreased glucose uptake, lactate production (aerobic glycolysis), and reduced anabolism (macromolecule synthesis) in various cancer cell lines." (PMID 24972138, 2014). "Cancers frequently show increased PI3K-Akt growth signaling and enhanced mammalian target of rapamycin (mTOR) activity." (PMID 24383451, 2014). "Reduced phosphorylation of mTOR was observed at 2 pm and 2 am in WAT samples from C26 tumour-bearing animals indicating inhibition of this regulator during cancer cachexia." (PMID 24667661, 2014). "Several signaling pathways kinases, such as mTOR, AMPK, PI3Ks, MAPKs (ERK and JNK), and PKC, respond to various external factors and are often dysregulated in cancer." (PMID 25375374, 2014). "In this cell line panel, we also examined the mTOR and ERK1/2 pathways, which are often deregulated in cancer." (PMID 24126619, 2013). "The first generation mTOR inhibitors, like rapamycin and its analogs everolimus (RAD001), temsirolimus (CCI-779) and ridaforolimus (AP23573), have been developed as cancer therapeutic agents." (PMID 23886294, 2013). "Small molecule inhibitors targeting dysregulated pathways (RAS/RAF/MEK, PI3K/AKT/mTOR, JAK/STAT) have significantly improved clinical outcomes in cancer patients." (PMID 23958373, 2013). "Future investigations are required to further delineate the roles and relationships of mTOR, ALDH, and OS cancer stem cells." (PMID 23476113, 2013). "PDK1 is a key component in phosphatidylinositol 3-kinase-Akt-mammalian target of rapamycin (PI3K-Akt-mTOR) signaling, a well-documented pathway that regulates cancer cell survival and proliferation." (PMID 24137444, 2013). "mTOR operates downstream from the PI3K signaling pathway, which is frequently up-regulated in cancer." (PMID 24216984, 2013). "The PI3 Kinase pathway is frequently deregulated in cancer and signaling downstream of PI3 Kinase involves proteins such as AKT, PDK and mTOR that control multiple cellular mechanisms." (PMID 23852390, 2013). "In the current studies, we demonstrated that c-Src is an immediate early signaling molecule that acts upstream of α6β4 dependent mTOR activation and subsequent translation of VEGF in MDA-MB-435/β4 and MDA-MB-231 cancer cells." (PMID 24180592, 2013). "The purpose of this review is to understand the role of mTOR inhibitors and miRNAs in carcinogenesis through targeting the mTOR signalling pathway and to determine whether they could have potential to be developed into novel therapies for a number of cancer types." (PMID 23434669, 2013). "Our results are in harmony with previous reports where rapamycin treatment has been shown to enhance autophagic activity in cancer cells by increasing LC3 II form and inhibiting the signaling of downstream molecules of the PI3K/Akt/mTOR pathway." (PMID 24205354, 2013). "Increased levels of eIF3f expression are found to compromise proliferation and promote apoptosis in cancer cells, of which this pro-apoptotic property of eIF3f is presumably dependent on its interplay with CDK11 and the mammalian target of rapamycin (mTOR)." (PMID 23725059, 2013). "Furthermore, a recent study reported that treatment with an mTOR inhibitor (WAY-129327) decreased endometrial proliferation, whereas mTOR activation was followed by loss of negative feedback to insulin receptor substrate-1 (IRS-1) during the early stages of cancer development." (PMID 23620761, 2013).